IL6 (interleukin 6)
Diseases named in the same sentence as IL6 in open-access papers (continued):
Sharing a sentence is not in itself a finding about the gene and the disease.
bacterial infection (651 papers, 2006 to 2026). "After obtaining nearly all of the results, we found that the variable “any bacterial infection” was statistically associated with IL-1β (p-value < 0.05), IL-6 (p-value < 0.05), IL-8 (p-value < 0.05), IL-10 (p-value < 0.05), and TNF-a (p-value < 0.05)." (PMID 40732663, 2025). "IL-6 is known to be induced not only by bacterial infections but also by stimulation from damage-associated molecular patterns (DAMPs) released from injured or dead cells." (PMID 40404957, 2025). "Proinflammation-associated factors of TNF-α and IL-6 in the tissue were studied to further confirm the inflammation regulation prompted by bacterial infection." (PMID 38167880, 2024). "Generally, the primary adverse effects of anti-IL-6/IL-6R antibodies are associated with bacterial infections." (PMID 39206193, 2024). "Upregulated IL-6 caused by bacterial infection inhibited caspase-1/-3 activation to suppress GSDMD-/GSDME-mediated pyroptosis and played a partially protective role." (PMID 38022612, 2023). "Nonetheless, limited research delves into the diagnostic utility of IL-6 and IL-10 in adult patients with bacterial infections." (PMID 37986183, 2023). "Interleukin-6 (IL-6), a pleiotropic cytokine, plays a crucial role in acute stress induced by bacterial infection and is strongly associated with reactive oxygen species (ROS) production." (PMID 38139043, 2023). "Up-regulated IL-6 caused by bacterial infection inhibited GSDMD/GSDME-mediated pyroptosis by suppressing caspase-1/3 activation and thus play partly protective role in bacterial infection." (PMID 38022612, 2023). "Cytokines associated with bacterial infections were downregulated (i.e., IL1β, IL6, IL8, TNFα), whereas the anti-inflammatory cytokine IL10 was upregulated." (PMID 36671404, 2022). "Its production is mostly targeted by the PAMP-mediated TLR signaling cascade and as a result, IL-6 gene-deficient mice display impaired defense against some bacterial infections." (PMID 36466847, 2022). "Pro-inflammatory cytokines associated with viral or bacterial infections such as tumor necrosis factor-alpha (TNFα), interleukin-6 (IL6), or interleukin-1beta (IL1β) are known to affect many liver functions or synthetic activities." (PMID 36499207, 2022). "Forty-three biomarkers were investigated, of which 6 (CRP, PCT, IL-8, IL-6, IL-10, and TNFα) were significantly associated with bacterial infection at admission, studied in multiple studies, and provided predictive data." (PMID 35372147, 2022). "The inflammatory factors TNF-α, IL-6, and IL-1β, are closely associated with the response to bacterial infection." (PMID 34858427, 2021). "Interleukin-6 (IL-6) is a serum biomarker that is released by fibroblasts, endothelial cells, macrophages, monocytes, and T2-lymphocytes in the presence of bacterial infections and associated tissue damage." (PMID 34572314, 2021). "The response of the TH 17-associated cytokines IL-6 and IL-17 has been shown to play an important role in bacterial infection in human S. aureus-associated OM and in animal models." (PMID 33109085, 2020). "C-reactive protein (CRP) was considered as one of the best markers for measuring inflammation caused by bacterial infection or tissue damage, which was produced by stimulation of interleukin-1 (IL-1) and interleukin-6 (IL-6) in liver." (PMID 32246038, 2020). "IL-6/IL-6R/JAK blockade therapeutics were reported to increase the risk of secondary bacterial infection." (PMID 33384605, 2020). "To investigate if IL-6 influences the susceptibility of IAV-infected animals to secondary bacterial infection, we monitored viral titer and bacterial load in WT and IL-6−/− mice." (PMID 32038632, 2019). "Specific inhibition of IL-6 trans-signaling holds the promise to be as effective as total IL-6 blockade, but with reduced side effects like enhanced susceptibility to bacterial infections." (PMID 28060820, 2017).
bacterial infection (continued). "As expected, bacterial infection caused IL-8 and IL-6 induction in both AGS-AC1 doxycycline- induced and -uninduced cells." (PMID 29085807, 2017). "The pretreatment of blood immune cells with EPs 7630 lowered their secretion of TNF-α and IL-10 and caused an IL-6 dominant response during second stimulation with viral or bacterial infection-mimicking agents." (PMID 26406906, 2015). "High serum IL-6 levels in severe cases of systemic inflammation with bacterial infections indicate that IL-6 increases the cell function with regard to immunity and the inflammation response, as confirmed by experiments with IL-6-deficient mice." (PMID 25360166, 2014). "Bacterial infection, including Wolbachia, has been linked with IL-8 production, so the levels of other lymphangiogenic mediators such as IL-8 and IL-6 will also need to be examined in this setting." (PMID 25010672, 2014). "Despite reports on its diagnostic application, IL-6 lacks specificity in the diagnosis of viral and bacterial infections." (PMID 24393388, 2014). "It is worth noting that the high IL-6 serum levels are capable of predicting the severity of bacterial infection, because they are associated with the development of systemic inflammatory response and progression to shock." (PMID 23690657, 2013). "Bacterial infections cause an acute form of inflammatory response leading to elevation of IL-6 production in the skin." (PMID 22792286, 2012). "Both TNF-α and IL-6 increase in bacterial infections, highlighting their diagnostic value in COM38." (PMID 40595978, 2025). "Proinflammatory cytokines such as IL-1β and IL-6 are integral to acute-phase inflammation that is linked to both systemic and metabolic alterations, while also modulating the immune response during bacterial infections." (PMID 41383965, 2025). "This might be attributed to the increased IL-6 production during bacterial infection, which caused an upsurge in hepatic CRP synthesis." (PMID 39946377, 2025). "IL-2, IL-6, and IL-17 are systemic pro-inflammatory cytokines, and IL-10 is an anti-inflammatory cytokine, the concentration of which increases in acute inflammatory processes and exacerbations of chronic diseases caused by a viral or bacterial infection." (PMID 39937802, 2025). "Moreover, increased IL-6 levels are associated with SI, disease progression, and bacterial infections, all of which are known to worsen outcomes in patients with ACLF." (PMID 41189884, 2025). "IL-6 is a key regulator of the inflammatory response and primarily produced in epidermal keratinocytes following damage caused by chronic skin diseases or bacterial infections." (PMID 39588538, 2024). "In summary, this study provides evidence that il-6 mutation attenuates oxidative stress during inflammation, thereby reducing liver injury, and offers information for the prevention and treatment of fish bacterial diseases in the future." (PMID 38139043, 2023). "Also, treatment with øKp_Pokalde_002 resulted in a significant reduction of pro-inflammatory cytokines (TNF-α and IL-6) caused by bacterial infection, thereby reducing the tissue inflammation." (PMID 34485172, 2021). "However, bacterial infections after parturition in the urogenital tract also lead to an increase of IL-6 and tumour necrosis factor alpha in the blood, causing a rise in body temperature." (PMID 34016189, 2021). "The production of IFNγ, TLR ligands, TNF-α, PGE2, IL-1β, and IL-6 from T cells or bacterial infection may follow the accumulation MDSCs associated with signal transducer and activator of transcription signaling pathways." (PMID 33212789, 2020). "Similarly, IL-6 also maintains host immunity as deficiency leads to failure of both innate and adaptive immune responses to viral and bacterial infections." (PMID 31936101, 2020).
bacterial infection (continued). "Genetic deficiencies of key mediators of the innate immune response, autosomal recessive IRAK4, and X-linked recessive IKBKG (encoding for NEMO) deficiencies, underlie pyogenic bacterial infection with impaired interleukin-6 (IL-6) production and C-reactive protein (CRP) production." (PMID 32067109, 2020). "Moreover, IL-6 deficiency leads to impaired innate and adaptive immunity to parasitic, viral, and bacterial infections." (PMID 33322581, 2020). "The research hypothesis is that the two IL6 variants display different expression patterns during temperature stress and during bacterial infection." (PMID 32466093, 2020). "Moreover, CTRP9 knockdown reduced the frequency of Granzyme B-producing T cells, impaired the transcriptional upregulation of Perforin A, Granzyme B, TNF-α, and IL-6, ultimately resulting in increased susceptibility to bacterial infection and elevated mortality." (PMID 41249580, 2025). "Furthermore, it has been demonstrated that immune disfunction such as the presence of anti-IL-6 autoantibodies may be associated with normal levels of CRP even in presence of a bacterial infection." (PMID 36673130, 2023). "While WT mice succumbed to bacterial infection within 11 days, Clec4a4−/− mice showed an enhanced survival rate (P<0.01), which was associated with significant reduction in splenic bacterial burden, and prominent elevation in serum productions of IL-6, IL-12p40 and IFN-γ." (PMID 27068492, 2016). "The cutoff value of serum IFN-γ/IL-6 ratio for differentiating PFAPA from bacterial infection was > 0.43, and the area under the receiver operating characteristic curve (AUC) was 0.79, with a sensitivity of 70.15% and a specificity of 71.88%." (PMID 41766872, 2026). "The level of serum IFN-γ, and the IFN-γ/IL-6 ratio in PFAPA patients were significantly higher than those in identified bacterial infection (p < 0.0001)." (PMID 41766872, 2026). "In response to bacterial infections, pro-inflammatory cytokines including IL-8, IL-6, TNF-α, and IL-1β are released, triggering neutrophil recruitment and new neutrophil production via G-CSF." (PMID 40766078, 2025). "Even more so, the more pronounced increase in IL-6 found in bacterial infection will override the ‘buffer capacity’ of sIL-6 receptors and sgp130, and high levels of CRP will be produced." (PMID 40632603, 2025). "In each case, Rab29-KO cells exhibited significantly higher IL-6 mRNA and protein levels compared to WT controls (p < 0.05), suggesting that Rab29 has a broad regulatory effect in reducing IL-6 expression across various bacterial infections." (PMID 41306588, 2025). "IL-6 is a pro-inflammatory cytokine released by macrophages and fibroblasts upon a bacterial infection." (PMID 40006601, 2025). "Common interleukins released by keratinocytes during bacterial infections include IL-1α, IL-6, IL-36, and TNF-α." (PMID 40856949, 2025). "IL‐6 promotes pro‐inflammatory responses to bacterial infections, enhancing T‐lymphocyte proliferation and B‐lymphocyte differentiation, activating the complement cascade, and inducing bone resorption." (PMID 40101934, 2025). "Procalcitonin (PCT) and interleukin-6 (IL-6) have gained attention as early indicators of bacterial infection and systemic inflammation." (PMID 41281040, 2025). "Since bacterial infection is marked by an increase in IL-6 and CRP levels, the usefulness of these markers after tocilizumab treatment is unclear." (PMID 39210228, 2025). "To investigate this discrepancy, we quantified IL-6 and TNF-α as main cytokines against bacterial infection by enzyme-linked immunosorbent assay (ELISA)." (PMID 40823821, 2025). "Together, these findings identify TBC1D9 as an essential and selective regulator of IL-6 expression in response to both cytosolic DNA sensing and diverse bacterial infection." (PMID 41306588, 2025).
bacterial infection (continued). "Biomarkers are also paving the way for precision medicine, where stratifying patients based on markers like IL-6 can tailor therapies, such as immunomodulators for cytokine storms or antibiotics for bacterial infections." (PMID 40310334, 2025). "Pro-inflammatory cytokines, such as IL-1β and IL-6, can trigger inflammatory responses, while anti-inflammatory cytokines, like IL-10, support the host immune system in defending against bacterial infections." (PMID 40403037, 2025). "CRP, PCT, and IL-6 are common diagnostic markers for bacterial infections, and when inflammation occurs, CRP, PCT, and IL-6 are released in large quantities and can be applied to evaluate treatment efficacy in patients." (PMID 40842537, 2025). "We found that the expression levels and secretion levels of IL-6, TNF-α and IL-1β were greater in Gpnmb-deficient THP-1 cells than in sgCtrl THP-1 cells upon bacterial infection." (PMID 40038549, 2025). "Given that TBC1D9 selectively regulates IL-6 expression in epithelial cells during cytosolic DNA sensing and bacterial infection, we then aimed to see if this regulatory pathway is also relevant in human disease." (PMID 41306588, 2025). "In bacterial infections, IL-6 is among the earliest cytokines released, initiating the acute-phase response." (PMID 40647525, 2025). "We used qRT-PCR to quantify the expression of inflammatory genes commonly elevated in bacterial infections including the chemokine Cxcl1, cytokines (Il22, Il17a, and Il6), and the bactericidal antimicrobial peptide Reg3g." (PMID 41502946, 2025). "In severe bacterial infection, the extremely high IL-6 levels overrun the so-formed IL-6 buffer, and CRP rises." (PMID 40632603, 2025). "Several studies have examined the influence of bacterial infection on the modulation of proinflammatory cytokines, such as IL-6 and IL-8, in IPEC-J2 cells." (PMID 40426498, 2025). "IL6 is involved in conceptus development and attachment in pigs and is known to be secreted in response to bacterial infection." (PMID 40188483, 2025). "Our study identifies TBC1D9 as a selective regulator of IL-6 expression in epithelial cells during innate immune responses to cytosolic DNA and bacterial infections." (PMID 41306588, 2025). "Biomarkers, including C-reactive protein (CRP), procalcitonin (PCT), and interleukin-6 (IL-6), in the bacterial infection group exhibited significantly elevated levels relative to the healthy controls (P < 0.0001)." (PMID 40046054, 2025). "Because of this, IL-6 serves as one of the earliest detectable markers in systemic bacterial infections." (PMID 40806991, 2025). "Our overall goal was to determine if targeting JAK or IL‐6 signaling provides a benefit during viral or viral/bacterial infection in a preclinical animal model." (PMID 39921246, 2025). "Cytokines such as TNF-α, IL-6, and IL-10, released during viral or bacterial infections, bind to specific receptors on C-fiber neurons of the vagus nerve, causing depolarization and increased excitability." (PMID 41044788, 2025). "In cytosolic DNA sensing and bacterial infection, selective IL-6 production in epithelial cells is controlled by complementary mechanisms." (PMID 41306588, 2025). "Our earlier research demonstrated that IL-6 levels in saliva can accurately detect bacterial infections in premature infants." (PMID 39857911, 2025). "Further analysis of pro-inflammatory factors IL-6 and IL-1β in serum showed that the IL-6 levels in the EI group were significantly lower than in the E group at 3 h and 12 h post-bacterial infection." (PMID 40895560, 2025). "The concentration of IL-6 in LT recipients can be significantly influenced by the onset of viral or bacterial infections, as well as by the administration of antibiotics and immunosuppressive agents such as high-dose steroids and cyclosporin A." (PMID 40505038, 2025). "Multiple studies have demonstrated IL-6’s high sensitivity and specificity in detecting bacterial infections at the onset of fever." (PMID 40647525, 2025).
bacterial infection (continued). "IL-6 and TNF-α played critical roles in bacterial infections, while RSV infection was directly associated with IL-8, an important chemokine involved in neutrophil recruitment." (PMID 40770421, 2025). "The upregulation of pro-inflammatory cytokines, including CXCL8, CXCL10, IL-1β, IL-6 and MMP9 was associated with the progression of host bacterial infection." (PMID 40839565, 2025). "Together, our data support a model in which the TBC1D9 regulates IL-6 expression through a Rab29-mediated pathway, balancing immune responses during bacterial infection." (PMID 41306588, 2025). "Interleukin-6 (IL-6) is a crucial cytokine activated during bacterial infections, coordinating the inflammatory response." (PMID 41306588, 2025). "As a pro-inflammatory cytokine, IL-6 is released by immune cells (e.g., macrophages and T cells) in response to bacterial infection to initiate C-reactive protein production, making it a sensitive marker to monitor inflammation." (PMID 40867936, 2025). "These cells produce key inflammatory cytokines such as tumor necrosis factor (TNF), interleukin 1 (IL‐1), and interleukin 6 (IL‐6) in the early phases of the response to bacterial infection." (PMID 41427018, 2025). "IL-6 is a proinflammatory cytokine that is usually excessively excreted in IPEC-J2 cells exposed to bacterial infections." (PMID 40426498, 2025). "This notable increase highlights the inflammatory response triggered by LPS, as it mimics bacterial infection and strongly induces cytokine production, including IL-6." (PMID 40243778, 2025). "Similar to the results of bacterial infection, IL-6 or TNF-α production in response to PAMP ligands was significantly increased in DDX5-deficient Mø." (PMID 38182816, 2024). "In bacterial infections, a CARD9 deficiency results in a decrease in inflammatory cytokines (IL-1β, IL-6, and TNF-α) and chemokines (CXCL1, CXCL2, and CXCL5)." (PMID 38473845, 2024). "IL-6, an essential component of the acute-phase reaction, shows high values in bacterial infections, with rapid increases during sepsis, and its levels correlate with the degree of diarrhea severity." (PMID 39062898, 2024). "As model biomarkers we chose three cytokines (interleukin-6, interleukin-8, tumor necrosis factor alpha), the bacterial infection marker C-reactive protein and the bacterial pathogen Streptococcus pneumoniae—all relevant factors in exacerbation episodes." (PMID 38834656, 2024). "Serum IL-6 is markedly increased in response to bacterial infection, activating monocytes and macrophages and inducing the release of CRP and PCT." (PMID 38504206, 2024). "Correspondingly, IL-6, IL-8 and MCP-1 levels in the cell culture supernatant were markedly elevated after bacterial infection, although statistically significant differences were observed only for IL-6 and MCP-1." (PMID 39035711, 2024). "Interleukin-6 (IL-6) is a key regulatory factor that is highly sensitive to early bacterial infections in newborns." (PMID 38848433, 2024). "In bacterial infection, inflammatory cytokines (such as tumor necrosis factor-alpha, IL-1β, and IL-6) induce gene expression responsible for PCT production." (PMID 38698211, 2024). "Both cytokines show increased values in acute gastroenteritis, but IL-6 levels are significantly higher in cases of bacterial infections." (PMID 39062898, 2024). "CRP is a marker of inflammation that increases during bacterial infection in response to cytokines IL-1 and IL-6 and has a stable decay rate." (PMID 38509997, 2024). "These cytokines, such as IL-6 and IL-8, are predictors of mortality in ACLF, with higher IL-6 or IL-8 plasmatic concentration when ACLF is precipitated by either bacterial infection or alcohol consumption, respectively." (PMID 38773651, 2024). "Although one child died of bacterial infection, IL-6 and other indicators decreased rapidly after early blood purification treatment, indicating that blood purification has a certain positive effect in managing cytokine storms." (PMID 39220151, 2024).